COLCA1 (colorectal cancer associated 1)
Synonyms: C11orf92; FLJ45803; CASC12; LOH11CR1F
Gene: Long non-coding RNA gene on chromosome 11 (111,290,787 to 111,305,498, reverse strand). Ensembl gene ENSG00000196167.
Subcellular location: Membrane
Diseases named in the same sentence as COLCA1 in open-access papers:
COLCA1 is named in the same sentence as 17 diseases in open-access papers, as found by Europe PMC text mining. Sharing a sentence is not in itself a finding about the gene and the disease. The quoted sentences say what the papers report.
colorectal cancer (11 papers, 2015 to 2025). A primary or metastatic malignant neoplasm that affects the colon or rectum. "COLCA2 was recognized as a colorectal cancer-associated gene, like COLCA1, and they were coregulated genes transcribed from opposite strands of a region of chromosome 11q23 associated with colon cancer." (PMID 35812248, 2022). "While COLCA1 was first thought to be related to the susceptibility of colorectal cancer, recent studies have pointed out its relationship with the exposure of primary biliary cholangitis." (PMID 35754800, 2022). "Common genetic variation at 11q23.1 is associated with colorectal cancer (CRC) risk, exerting local expression quantitative trait locus (cis-eQTL) effects on POU2AF2, COLCA1 and POU2AF3 genes." (PMID 39609081, 2025). "The detrimental effects of heavy drinking on colorectal cancer were suggested by studies using the COLCA1/COLCA2 and ALDH2 genotypes as indicators of alcohol exposure." (PMID 39311360, 2024). "In this signature which consisted of nine prognostic lncRNAs related to redox genes, COLCA1 has been reported and identified as a key lncRNA in colorectal cancer, and DLEU2 has been reported related to the development of multiple cancers." (PMID 33425212, 2020). "The CRC risk variant, rs3802842, is located at 11q23 in the intronic regions of two overlapping genes, the colorectal cancer associated 2 and 1 (COLCA2 and COLCA1) genes." (PMID 28506205, 2017). "Finally, we mapped the RLOC_00005829 sequence on the human genome, and showed that it clearly aligned to the COLCA1 gene (identity = 61.1%), a GENCODE-annotated antisense lncRNA that was already associated with human colorectal cancer by GWAS." (PMID 31234577, 2019). "Also, three meQTLs have been identified in colorectal cancer GWAS: rs9271770 related with HLA-DQA1, rs3087967 related with C11orf53 and rs3802842 intronic to COLCA1 and COLCA2 genes." (PMID 34419169, 2021).
colon cancer (4 papers, 2017 to 2025). "Genetic, expression and immunohistochemical data implicate COLCA1 and COLCA2 in the pathogenesis of colon cancer, whereas histologic analyses indicate the involvement of immune pathways." (PMID 28052013, 2017).
asthma (1 paper, 2022). "Similarly, the following results showed that the DElncRNAs with the top five AUCs of the T2 asthma and non-T2 asthma groups: PCAT19 (AUC = 0.914), COLCA1 (AUC = 0.827), SLC9A3-AS1 (AUC = 0.824), SNHG16 (AUC = 0.802), and LINC01133 (AUC = 0.793)." (PMID 35480331, 2022).
atherosclerosis (1 paper, 2023). A disease characterized by the build-up of fatty material and calcium deposition in the arterial wall resulting in partial or complete occlusion of the arterial lumen. "In addition, Ming-Peng and colleagues indicated the potential significance of the COLCA1 (colorectal cancer associated 1)/miR-371a-5p/SPP1 axis in atherosclerosis-related inflammation." (PMID 37508497, 2023).
colorectal tumors (1 paper, 2017). "Since lower expression levels of COLCA2 and COLCA1 is associated with the risk allele and lower expression levels of COLCA2 and COLCA1 were observed in colorectal tumors versus normal tissue." (PMID 28506205, 2017). "It was associated with expression of COLCA2, COLCA1, and c11orf53 in normal transverse colon tissue but not in sigmoid colon or colorectal tumor tissue." (PMID 28506205, 2017). "The cis-eQTL analysis with the proxy SNP demonstrated similar expression patterns in the colorectal tumor tissue samples, where the risk allele associated with lower expression levels compared to the reference allele for the COLCA2 (p = 8.90 × 10−4) and COLCA1 (p = 4.70 × 10−3) genes." (PMID 28506205, 2017).
lymph node metastasis (1 paper, 2021). "Half of this lncRNA expression was significantly correlated with lymph node metastasis, and most of these lncRNA expressions in late stage (stage III‐IV) were significantly different from early (stage I‐II), and the expression levels of two lncRNA (COLCA1 and TRG‐AS1) were associated with T stage." (PMID 34558724, 2021).
tumor (6 papers, 2017 to 2025). "Additionally, MeRIP-qPCR assays validated that SOCAR and SNHG8 transcripts were hypermethylated, and PCAT19 and COLCA1 transcripts were hypomethylated in LUAD tumor tissues." (PMID 37029420, 2023). "Eosinophils can induce apoptosis and kill tumor cells via releasing ECP, EDN, TNF and granzyme, while mast cells may be damaging to tumor cells through cytokines and proteolytic enzyme secretion, indicating that COLCA1 may exert its tumoricidal functions through immunity." (PMID 35102554, 2022). "According to our above results, we tried to find which lncRNA was significant in tumor and normal differential expression, prognostic ability, and tumor staging power and found that AC107464.3, LINC01711, and COLCA1 occupied the top 3 most counts of cancer types, which was 7, 6, and 5, respectively." (PMID 36874011, 2023). "In another study, four lncRNAs (SNHG3, RMST, ZNF667-AS1,and COLCA1) were demonstrated to be significantly dysregulated according to the next-generation sequencing on a cohort containing 48 renal cell carcinoma paired tumor and non-tumor tissues, and further validated by qPCR." (PMID 41042421, 2025).
cancer (4 papers, 2023 to 2025). A tumor composed of atypical neoplastic, often pleomorphic cells that invade other tissues. "The results showed that LINC01711, AC107464.3, LINC00324, COLCA1, and PRKAG2-AS1 were the top five lncRNAs, and they were differentially expressed in cancer stages of 12, 8, 8, 8, and 8 cancer types, respectively." (PMID 36874011, 2023). "Furthermore, pan-cancer analysis has identified AC026471.3, AL691432.2, COLCA1, ITGB1-DT, and LINC01833 as the top five lncRNAs in our signature exhibiting the most significant difference between pan-cancer tumors and normal tissue." (PMID 38011277, 2023). "The remaining 4 lncRNAs (COLCA1, AC091057.1, AL355001.1, and DIP2A-IT1) have no relevant research in cancer." (PMID 37258567, 2023).
COLCA1 also shares sentences with these, for which no sentence is quoted: primary biliary cholangitis (2 papers); dementia (1); endometrial cancer (1); gastric cancer (1); inflammatory bowel disease (1); lung adenocarcinoma (1); lung carcinoma (1); rectal cancer (1); serous ovarian cancer (1).